FGFR4 (fibroblast growth factor receptor 4)
Diseases named in the same sentence as FGFR4 in open-access papers (continued):
Sharing a sentence is not in itself a finding about the gene and the disease.
ovarian carcinoma (17 papers, 2016 to 2026). A malignant neoplasm originating from the surface ovarian epithelium. "In ovarian cancer, the overexpression of FGFR4 was significantly associated with decreased overall survival duration." (PMID 39858026, 2025). "For instance, FGFR4-positive staining is associated with postoperative residual disease in ovarian cancer." (PMID 40393028, 2025). "On the other hand, a Gly388Arg mutation in FGFR4 has been reported in ovarian cancer and was associated with increased patient survival." (PMID 33193890, 2020). "In OC research, targeting FGFR4 with siRNA and the FGFR4 trap protein can significantly inhibit the progression of ovarian cancer." (PMID 41328353, 2026). "The inhibition or silencing of FGFR4 was shown to suppress tumor progression in preclinical ovarian cancer models in vitro and in vivo." (PMID 39858026, 2025). "This study has demonstrated the therapeutic potential of targeting the SORL1/FGFR4 pathway to improve the chemoresponse of patients with recurrent and/or resistant ovarian cancer." (PMID 39858026, 2025). "Our findings support the potential of FGFR4 inhibitors as new therapeutic agents for ovarian cancer." (PMID 39858026, 2025). "This study also demonstrated the potential of targeting SORL1 with an antibody blocker or targeting FGFR4 with a small molecule inhibitor as new strategies to improve the response to chemotherapy in patients with recurrent and resistant ovarian cancer." (PMID 39858026, 2025). "Our findings suggest that the anti-SORL1 antibody and a small molecule inhibitor specific to FGFR4 both have the potential to overcome carboplatin resistance in ovarian cancer cells." (PMID 39858026, 2025). "To better assess the tumor-suppressing potential specifically due to the inhibition of FGFR4, we evaluated the effect of small molecular FGFR4 inhibitors on ovarian cancer cell lines in vitro and in vivo." (PMID 39858026, 2025). "Due to the overexpression of FGFR4 in ovarian cancer and its role in promoting cancer cell proliferation, FGFR4 inhibitors have therapeutic potential in ovarian cancer." (PMID 39858026, 2025). "Our data also suggest that SORL1 interacts with EGFR and FGFR4, and their interactions are required to maintain the high levels of EGFR and FGFR4 proteins in ovarian cancer cells." (PMID 39858026, 2025). "In a study of ovarian cancer, FGFR4 was shown to be a prognostic indicator in advanced-stage disease, and inhibition of FGFR4 with siRNA significantly inhibited ovarian tumor growth in vivo and in vitro." (PMID 38540215, 2024). "In another study, FGFR4 expression was observed in ovarian cancer, especially in HGSCs of patients with residual disease after initial surgery." (PMID 37789421, 2023). "Nonetheless, the survival analysis of the ovarian cancer population showed consistent results with the previous study, showing that patients with a high expression of FGFR4 presented a poor survival rate." (PMID 34639155, 2021). "Another study revealed that the higher expression of FGFR4 is correlated with a poorer overall survival rate in patients with ovarian cancer." (PMID 34639155, 2021). "Further, genomic studies of epithelial ovarian cancer have been able to identify the FGFR4 pathway and its inhibitor BIBF-1120, which has the potential to block cancer progression." (PMID 29068423, 2017). "Regulation of EGFR and FGFR4 facilitated by SORL1 promotes chemoresistance in ovarian cancer." (PMID 41328353, 2026). "Therefore, we propose to further explore the potential of FGFR4 inhibitors in targeting recurrent ovarian cancers." (PMID 39858026, 2025). "Among these genes, we identified sortilin-related receptor 1 (SORL1) and its role in promoting carboplatin resistance through regulating the stability of epidermal growth factor receptor (EGFR) and fibroblast growth receptor 4 (FGFR4) using ovarian cancer models in vitro and in vivo." (PMID 39858026, 2025).
ovarian carcinoma (continued). "We further revealed that SORL1 interacts with EGFR and FGFR4, which may contribute to maintaining the levels of EGFR and FGFR4 proteins in ovarian cancer cells." (PMID 39858026, 2025). "Hence, it is obvious that further studies are required to elucidate how MAEL regulates the expression of FGFR4 and therefore promotes the metastasis of ovarian cancer." (PMID 35513870, 2022). "Inhibiting FGFR4 and its ligand markedly reduces ovarian tumor growth both in vitro and in vivo, indicating that FGFR4 could also be a promising therapeutic target in ovarian cancer that has high expression of FGFR4." (PMID 32154250, 2020). "These novel tools specify FGFR4 as a potential pathway, which could offer targeted therapy to epithelial ovarian cancer patients with a specific, enriched activation of this pathway." (PMID 29068423, 2017). "Our data showed that a selective inhibitor of FGFR4, FGF401, can improve the therapeutic efficacy of carboplatin in a xenograft mouse model of ovarian cancer." (PMID 39858026, 2025). "In the ovarian cancer cell line OVCAR8, we demonstrated that treatment with this antibody at 10 μg/mL for 24 h downregulated the levels of EGFR and FGFR4." (PMID 39858026, 2025). "FGF1 expression and secretion are increased in ovarian cancer associated fibroblasts (CAFs), which, when cultured with the SKOV3 human ovarian cancer cell line, increases ERK1/2 activity through activation of FGFR4." (PMID 34068954, 2021). "Our findings also suggest that the interaction of SORL1 with EGFR and FGFR4 may play a role in increasing the levels of EGFR and FGFR4 proteins in ovarian cancer cells." (PMID 39858026, 2025). "The therapeutic potential of FGFR4 selective inhibitors has not been investigated in ovarian cancer models." (PMID 39858026, 2025). "However, we could not observe a significant difference in FGFR4 expression between normal and cancer tissues, whereas the previous study reported the upregulation of FGFR4 in ovarian cancer tissues compared to the adjacent normal tissues." (PMID 34639155, 2021).
melanoma (15 papers, 2006 to 2025). A malignant, usually aggressive tumor composed of atypical, neoplastic melanocytes. "Loss-of-function mutations in FGFR2 and activating mutations in FGFR4 have been connected with melanoma." (PMID 31167513, 2019). "The analysis of the literature has shown the lack of unambiguous evidence of the pro-tumorigenic and pro-metastatic impact of FGFR4 Arg388 allele in the majority of cancers, including melanoma." (PMID 31167513, 2019). "Nevertheless, independently from this specific polymorphism, FGFR4 seems to play an important role in melanoma considering the high expression rates in advanced tumours and the positive correlation with worse clinical outcome." (PMID 16721364, 2006). "The present study demonstrates an association between FGFR4 in melanoma and clinical and histopathologic parameters indicative of progression." (PMID 16721364, 2006). "In order to validate the influence of FGFR4 and its Arg388 polymorphism in melanoma, a large patient cohort with long-term follow-up of up to 141 months was evaluated for FGFR4 protein expression in addition to the FGFR4 genotype." (PMID 16721364, 2006). "Genotype analysis of the Gly388 allele and the Arg388 allele of FGFR4 was performed in 185 melanomas by polymerase chain reaction-restriction fragment length polymorphism (PCR-RFLP)." (PMID 16721364, 2006). "Regarding the genotypes of FGFR4 in melanoma patients, 55% (101/185) had a homozygous Gly allele, while 45% (84/185) showed at least one Arg388 allele." (PMID 16721364, 2006). "Furthermore, FGFR4 Arg388 polymorphism was analysed in 185 melanoma patients by polymerase chain reaction-restriction fragment length polymorphism (PCR-RFLP)." (PMID 16721364, 2006). "Therefore, it has been suggested that rather than serving as predisposition indicators, genetic aberrations in FGFR2 and FGFR4 might be used as potential biomarkers of melanoma progression." (PMID 31167513, 2019). "Furthermore, Kaplan–Meier survival analysis for a mean follow-up time of 72 months revealed that expression of FGFR4 in melanoma was associated with reduced overall survival (P=0.047) as well as reduced disease-free survival (P=0.024) of the respective patients." (PMID 16721364, 2006). "Subgroup analyses showed that the mutation frequencies of melanoma regarding FGFR1, FGFR2, FGFR3 and FGFR4 ranked 1st, 2nd, 2nd, and 2nd across all cancers, respectively." (PMID 36426352, 2022). "In this study, the focus is on FGFR4 in melanoma analysing its expression and different genotypes in relation with pathological and clinical parameters." (PMID 16721364, 2006). "The number of FGFR4-expressing melanoma cells per tumour was 100% in 20 cases, 50–99% in 10 cases, 10–49% in 21 cases and 1–9% in 10 cases." (PMID 16721364, 2006). "The cytoplasmic staining of the FGFR4 in melanoma cells is in agreement with other publications investigating the expression for FGFR4 in other types of cancer." (PMID 16721364, 2006). "In 45% (61/137) of the tumours, FGFR4 was detected with varying staining intensities in the cytoplasm of the melanoma cells." (PMID 16721364, 2006). "When comparing FGFR4 protein expression and number of primary tumours, 22 (65%) of 34 patients with more than one melanoma were positive for FGFR4 (P=0.022)." (PMID 16721364, 2006). "This is supported by our additional findings that FGFR4 was significantly overrepresented in the group of melanoma patients with metastases." (PMID 16721364, 2006). "Comparing the expression with clinical data of melanoma patients there was a significant correlation between FGFR4 protein expression and pTNM stage according to UICC and AJCC classification." (PMID 16721364, 2006). "In conclusion, the previously observed genotype-dependent difference in disease progression suggests that FGFR4 Arg388 as a marker for tumour progression in different cancers can only partly be demonstrated in melanoma." (PMID 16721364, 2006).
melanoma (continued). "In melanoma cells resistant to trametinib, few damaging mutations were found including L437F and K438M substitutions in ERBB4 in 11_TRAR, G388R variant of FGFR4, and E36A variant of platelet-derived growth factor receptor alpha (PDGFRA) in 21_TRAR, and E519K alteration of RASGRP4 in 17_TRAR cells." (PMID 31936151, 2020). "FGFR4 has been detected at the protein level in 45% of 137 melanoma specimens." (PMID 31167513, 2019). "In a large nested case-control study of Caucasian women, however, neither mutations in FGFR2 nor in FGFR4 has been found as contributing to an inherited predisposition to three skin cancer types, including melanoma, SCC, and BCC." (PMID 31167513, 2019). "Similarly, as for genotypes of FGFR4 in breast, colorectal, and lung cancers, an SNP (rs351855) that results in Gly388Arg substitution can be found in melanomas." (PMID 31167513, 2019). "FGFR4 levels are largely increased in various melanoma cell lines." (PMID 30577533, 2018). "In conclusion, the Arg388 genotype and the protein expression of FGFR4 may be potential markers for progression of melanoma." (PMID 16721364, 2006). "By immunohistochemical analysis, 137 different primary melanomas could be evaluated for protein expression of FGFR4." (PMID 16721364, 2006). "The presence of FGFR4 may facilitate the proliferative and angiogenic effects of bFGF and thus confer an increased metastatic potential to the melanoma cells." (PMID 16721364, 2006). "In addition, 31 of 56 (55%) melanoma patients with metastatic disease showed FGFR4 protein expression (P=0.025)." (PMID 16721364, 2006). "Tumour vascularity was evaluated on 137 melanoma tissues and compared to the expression of FGFR4." (PMID 16721364, 2006). "Furthermore, patients with FGFR4-expressing tumours had more often additional melanomas in the past." (PMID 16721364, 2006). "FGFR4 was expressed in 45% of 137 primary melanomas with different intensities." (PMID 16721364, 2006). "Moreover, a significant association between FGFR4 protein expression and microvessel density was observed and an increased number of proliferating Ki-67-positive melanoma cells was found at the edges and at the infiltrating front of FGFR4-postive tumours." (PMID 16721364, 2006). "About half of the population carries a homozygous or heterozygous FGFR4-G388R SNV, which has been associated with poor prognosis in various tumor types, such as adenocarcinomas of the breast, prostate, and colon, as well as squamous cell carcinomas and melanomas of the head and neck." (PMID 40806692, 2025). "This may hint to a role of FGFR4 in melanoma development, even though the mechanism is unknown." (PMID 16721364, 2006). "Based on functional in vitro investigations in stable cell lines and patient-derived explant models, we identified FGFR4 as central mediator of GBM cell aggressiveness, as previously published for melanoma." (PMID 35484633, 2022). "FGFR1 and to some extent FGFR4 are exceptional in contrast to FGFR2-3, and these receptors are expressed in the majority of melanomas." (PMID 31167513, 2019). "Melanoma patients harboring FGFR4 Mut showed a similar tendency, whose survival was longer than those with FGFR4 Wt, though the difference was not statistically significant (mOS: 49.27 months vs. 31.30 months; HR 0.66, 95%CI 0.40-1.09; P = 0.17)." (PMID 36426352, 2022). "Therefore, both, expression of FGFR4 and Arg388 genotype was suggested as potential biomarkers for the progression of melanoma, although no further study has been published to extend these findings." (PMID 31167513, 2019). "The majority of early-stage melanoma did not express FGFR4 in contrast to advanced-stage melanomas." (PMID 16721364, 2006). "Besides melanoma cells keratinocytes, fibroblasts, nerves, smooth muscle cells, sweat glands and sebaceous glands were stained for FGFR4, but not melanocytes." (PMID 16721364, 2006).
pancreatic cancer (15 papers, 2006 to 2025). "The FGFR4 expression was associated with pancreatic cancers (Leung, Gullick, & Lemoine, 1994)." (PMID 31207142, 2019). "Increased FGFR4 expression has been detected in various cancers, including lung, liver, kidney and pancreatic cancer, making it a potential drug target." (PMID 40547312, 2025). "The overexpression of FGFR4 in pancreatic cancer is found to be mediated by an intronic enhancer that is activated by HNF1A, and mutations in the HNF1A-binding site reduced the enhancer activity." (PMID 34035238, 2021). "FGFR4 was expressed in a majority of pancreatic cancer patients, and its expression was related to longer overall survival." (PMID 30945363, 2019). "Next, the association between FGF19, FGF21, FGFR1, FGFR4, and KLB overexpression and the overall survival of pancreatic cancer patients was evaluated." (PMID 30593273, 2018). "FGFR4 is reportedly overexpressed in various cancers, such as breast, prostate, hepatocellular, ovarian, gastric, colorectal, and pancreatic cancer, where it may contribute to tumor progression." (PMID 33066597, 2020). "For example, in models of pancreatic cancer, we discovered that HMGA1 activates pathways downstream of the fibroblast growth factor, FGF19, and inhibitors of FGF19 and its receptor (FGFR4) are already available in the clinic." (PMID 40076747, 2025). "Although high expression of FGFR4 was observed in OPSCC and pancreatic cancer, FGFR4 does not show prognostic significance in these cancers." (PMID 32154250, 2020).
Obesity (14 papers, 2012 to 2025). Accumulation of substantial excess body fat. "Further definitions of the BA/FXR/FGF19/FGFR4 axis phenotypes, and their relevance to disease, whether primary, caused by genetic polymorphisms, or secondary to acquired factors such as obesity or metformin, is an area of on-going research, both in BAD and in NAFLD and NASH." (PMID 30682184, 2019). "The hypermetabolic 2 SD and 3 SD effects of Fgfr4+/-, Fgfr4-/-, and Acer1-/- contribute to resistance to obesity, while the effects of Pparg heterozygosity are modest at just over 1 SD." (PMID 32356724, 2020). "Further studies are warranted to determine the relative contribution of the increased plasma FGF15 levels versus bile acids in this regard, and to determine if there are any other factors that also mediate the FGFR4 ASO-induced anti-obesity effect." (PMID 23922646, 2013). "Taken together, these data demonstrate that the upregulated FGF15 levels in the DIO mice after FGFR4 ASO treatment is a major mediator for the FGFR4 ASO-induced anti-obesity effect." (PMID 23922646, 2013). "Mechanistic studies indicated that anti-obesity effect of FGFR4 ASO was mediated at least in part through an induction of plasma FGF15 level resulted from reduction of hepatic FGFR4 expression." (PMID 23922646, 2013). "Here we report that treatment of diet-induced obese (DIO) mice with fibroblast growth factor receptor 4 (FGFR4) ASOs showed a significant anti-obesity effect and other metabolic improvements." (PMID 23922646, 2013). "Furthermore, the FGF15/FGFR4/ERKsignaling pathway was significantly activated in skeletal muscle,which contributed to obesity-related sarcopenia prevention and improvementin glucose homeostasis." (PMID 40193085, 2025). "This FGFR4 ASO anti-obesity effect persisted in animals with limited calorie intake." (PMID 39944202, 2025). "This study demonstrates that FGFR4 inhibition may be a potential therapeutic approach for the treatment of obesity and related metabolic disorders." (PMID 39944202, 2025). "In severe obesity, alterations in enterohepatic signaling or fibroblast growth factor receptor 4 responsiveness may occur independently of histological liver injury." (PMID 40943431, 2025). "This anti-obesity effect of FGFR4 ASO was maintained in caloric restricted animals." (PMID 23922646, 2013). "Therefore, FGFR4 could be a potential novel target and antisense reduction of hepatic FGFR4 expression could be an efficacious therapy as an adjunct to diet restriction or to an appetite suppressant for the treatment of obesity and related metabolic disorders." (PMID 23922646, 2013). "Thus, increased plasma bile acids after FGFR4 ASO treatment may also play some positive role in mediating FGFR4 ASO-induced anti-obesity effect." (PMID 23922646, 2013). "In our results, the induction of the mRNA levels of adiponectin, FgfR1, FgfR4 and Egr1 in scWAT of HFDM mice indicates that, in obesity, maqui supplementation increases the sensitivity to FGF21 of scWAT." (PMID 31480627, 2019). "The mRNA levels of JMJD3 and KLB were decreased, whereas those of Fgfr1 and Fgfr4 were increased, after feeding a HFD, suggesting that decreased expression of KLB may contribute to FGF21 resistance in obesity." (PMID 32042044, 2020). "The anti-obesity efficacy of FGFR4 ASO was primarily due to increased basal EE (coupled with decreased lipogenesis), as supported by the following evidence: First, FGFR4 ASO treatment increased whole body O2 consumption and heat production without changing food consumption or locomotor activity." (PMID 23922646, 2013).